TLR2 (toll like receptor 2)
Diseases named in the same sentence as TLR2 in open-access papers (continued):
Sharing a sentence is not in itself a finding about the gene and the disease.
COVID-19 (continued). "For the two markers, the protective factor was the homozygous genotype for a minor allele: rs744166 in the STAT3 gene for susceptibility to COVID-19 and rs1898830 for the TLR2 gene for the progression of the disease to severe form." (PMID 35327350, 2022). "In addition to its direct interaction with SARS-CoV-2 components, the activity of TLR2 is functionally linked to host innate immune components that contribute to the immunopathology and severity of COVID-19." (PMID 41011507, 2025). "-TLR2 and MyD88 are associated with the severity of COVID-19." (PMID 41011507, 2025). "Further studies investigating whether TLR2 polymorphisms in the general population correlate with COVID-19 disease severity may contribute to an improved understanding of the molecular determinants of COVID-19 outcomes." (PMID 39240187, 2024). "However, the TLR2 action mechanism in the CRS associated with COVID-19 requires further confirmation." (PMID 38165854, 2024). "In MIS-C and KD, as in severe COVID-19, the additional synergisms are due to receptors associated with bacterial antigen activation, particularly TLR2 and TLR4, and are consistent with high observed rates of bacterial co-infections in severe COVID-19 patients who develop MIS-C (Introduction)." (PMID 36769320, 2023). "Moreover, TLR2 expression is linked to COVID-19 severity and is prominent in β-coronavirus-induced inflammatory responses; TLR2-dependent signaling triggers pro-inflammatory cytokine production during infection, regardless of viral entry." (PMID 37233676, 2023). "In addition, the expression of TLR2 and its cofactor MyD88 is associated with enhanced inflammatory responses, particularly in critically ill COVID-19 patients with severe disease." (PMID 35632741, 2022). "SARS-CoV-2 infection also increases the expression of TLR2 and other molecules, such as melanoma differentiation-associated gene 5 (MDA5), ACE2 and interferon regulatory factor 3 (IRF3), and the expression of TLR2 is positively associated with the severity of COVID-19." (PMID 35832809, 2022). "Feys and colleagues found that several signals of immune paralysis, including suppressed TLR2 expression, were shared between patients with IAPA- and COVID-19-associated pulmonary aspergillosis." (PMID 40197039, 2025). "We further demonstrate that both the trimeric full-length Spike protein and its monomeric fragments—generated during infection—contribute to the COVID-19-associated CSS, likely via TLR2 and inflammasome activation." (PMID 41567221, 2025). "The genomic analysis of different data sets showed significantly elevated TLR2 expression in the peripheral blood mononuclear cells of COVID-19 patients, while potential therapeutic drug analysis was performed for this target." (PMID 38165854, 2024). "In this study we demonstrated that the expression of TLR2 similarly was significantly higher in the lungs of patients with lethal COVID-19 when compared to the control group of SARS-CoV-2-negative lungs." (PMID 38786077, 2024). "At the same time, a correlation was found between the level of TLR2 expression and the severity of the disease, which emphasizes the important role of TLR2 in the pathogenesis of COVID-19." (PMID 39457048, 2024). "The expression of TLR-2 increases following SARS-CoV-2 infection, and it is positively associated with the severity of COVID-19." (PMID 39456843, 2024). "We studied the relationship between FURIN, IFNL4, and TLR2 genotypes and laboratory parameters in COVID-19 patients, particularly ALT as a marker of liver injury." (PMID 38703289, 2024). "Specifically, using digital pathology-based immunohistochemistry, we found that COVID-19 patients had a mean count of TLR-2-positive macrophages of 128.08 ± SEM 21.789, while the control cases had a mean count of 16.33 ± SEM 5.29." (PMID 38786077, 2024).
COVID-19 (continued). "It is necessary to understand the importance of host immunogenetic heterogeneity in the TLR2 gene for the evolution of COVID-19 to create strategies to cope with the disease." (PMID 37895256, 2023). "We found that the expression of TLR2 increased with the severity of COVID-19 in both PBMCs and monocytes (respectively), similar to what was observed with IL27 subunits." (PMID 37310504, 2023). "Complementing these results, our analysis of RNA-Seq data in BALF from severe COVID-19 patients showed an upregulation in the Epstein-Barr virus infection pathway, which is known to involve TLR2-MyD88 signalling." (PMID 38034686, 2023). "In COVID-19, TLR2 has been shown to be the primary innate sensor of the envelope protein of SARS-CoV-2, generating a cytokine response mediated via the MYD88 pathway with the subsequent activation of NF-κB and MAPK signalling." (PMID 36851206, 2023). "In this study, we evaluated the immunogenicity and protective efficacy of an experimental COVID-19 vaccine comprising the SARS-CoV-2 Spike trimer adjuvanted with the TLR2 agonist, LP1569, and the STING agonist, C-di-GMP, named Spike-LP-GMP." (PMID 37179389, 2023). "Here, we observed that, at admission, COVID-19 patients had a low response to the agonist of TLR2, TLR4, TLR7/8, and TLR9, suggesting a TLR cross-tolerance." (PMID 37189696, 2023). "Several TLRs (TLR1, TLR2, TLR4, etc.)have an association with disease progression in patients with COVID-19." (PMID 37158916, 2023). "Patients with severe/critical COVID-19 were also characterized by an increased activation of TLR2 pathway with enhanced expression of TLR2 RNA in the circulating mononuclear cells, when compared with moderate COVID-19 or healthy subjects." (PMID 36941580, 2023). "COVID-19 disease severity has also been correlated with TLR2 and MYD88 expressions, and it has been observed that TLR2 senses the SARS-CoV-2 envelope protein to produce inflammatory cytokines." (PMID 37325475, 2023). "This suggests that acute infection with COVID-19 can trigger a persistent and sustained activation of TLR2, thereby enhancing fibrogenesis in the kidneys." (PMID 37626956, 2023). "In COVID-19, the S2E protein alone causes acute respiratory distress syndrome (ARDS)-like pathological damage by activating toll-like receptor 2 (TLR2) on macrophages and triggering the secretion of cytokines and chemokines." (PMID 36082238, 2022). "Researchers found that TLR2 and MYD88 expression were both associated with the severity of COVID-19." (PMID 36575422, 2022). "Among the enriched MFs, the lipopolysaccharide (LPS) immune receptor activity driven by TLR2 hub-DEG is associated with the LPS-induced production of pro-inflammatory cytokines reduction, inflammation by affecting the lungs LPS due to the COVID-19 infection." (PMID 35277538, 2022). "Together, these data suggest an association of MyD88 and a panel of TLRs (i.e., TLR1, TLR2, TLR4, TLR5, TLR8, and TLR9) with disease progression in patients with COVID-19." (PMID 35682644, 2022). "Inhibition of TLR2 and its downstream signaling pathways in the body can prevent and control the occurrence of COVID-19." (PMID 36188605, 2022). "Zheng and colleagues used public data sets to analyze t the expression of TLRs and downstream adaptor proteins in COVID-19 patients with varying degrees of disease progression revealed that E protein can activate TLR2 and downstream immune signaling pathways." (PMID 36188605, 2022). "Further, a single-cell computational analysis identified TLR2 as a key gene involved in exacerbating the hyperinflammatory response seen in patients with severe COVID-19." (PMID 36419185, 2022). "A recent study shows that TLR2 and Myd88 are implicated in SARS-CoV-2-induced inflammatory response and are associated with COVID-19 disease severity." (PMID 35445287, 2022). "Lung cells from COVID-19 patients show expression of HIF1α, TLR2, TLR4, PFKFB3, CXCR1, −2 and −4, SOD2, PLAUR and other genes expressed in immature myeloid cells." (PMID 33345622, 2021).
COVID-19 (continued). "For example, the U.S. FDA has approved an investigation into the efficacy of a PUL-042 inhalation solution that blocks TLR2/6/9 to reduce the infection rate, progression, and disease severity of COVID-19 (NCT04312997, NCT04313023)." (PMID 34834939, 2021). "TLR-2, TLR-3, and TLR-4 activation by COVID-19 causes the release of inflammatory cytokines such as IL-1β." (PMID 33082858, 2020). "In summary, hyperinflammation driven by TLR2/4 activation in both the CNS and the periphery, resulting from its interaction with the S protein, can trigger neurological symptoms and exacerbate myocarditis and multiple organ damage in COVID-19 patients." (PMID 40431631, 2025). "This suggests that TLR2 antagonists could be an effective treatment for severe inflammation in patients with severe COVID-19." (PMID 41011507, 2025). "TLR2 plays a crucial role in the immune response to infectious diseases like COVID-19." (PMID 40533467, 2025). "IL6R, TLR4, TLR2, and IFNG may be potential pathogenic genes and therapeutic targets for the CRS associated with COVID-19." (PMID 38165854, 2024). "Moreover, TLR-2 was upregulated in the lung macrophages of a subset of COVID-19 patients who passed away." (PMID 38786077, 2024). "TLR2 expression was found to increase with COVID-19 severity." (PMID 38703289, 2024). "In conclusion, this study revealed that IL-6R, TLR4, TLR2, and IFNG may be potential pathogenic genes in the CRS associated with COVID-19." (PMID 38165854, 2024). "However, in contrast to the control group of SARS-CoV-2-negative lungs, our analysis revealed a trend toward TLR-2 up-regulation in the lungs of a subgroup of patients with deadly COVID-19." (PMID 38786077, 2024). "Several TLRs, such as TLR2, TLR3, TLR4 and TLR7, have been associated with COVID-19 severity." (PMID 37175768, 2023). "TLR2 expression was associated with COVID-19 severity, being identified as a sensor of SARS-CoV-2 that drives inflammatory cytokine production, potentially contributing to the dysregulated immune response observed in patients with severe COVID-19." (PMID 37175768, 2023). "Furthermore, there is evidence that activation of the NF-kB inflammatory pathway in COVID-19 (a disease aggravating factor) by protein S is dependent on TLR2 signaling." (PMID 37895256, 2023). "TLR2, TLR3, TLR4 and TLR7 have been associated with COVID-19 severity." (PMID 37175768, 2023). "Therefore, the induction of TLR2 by the human innate immune system probably has more unfavorable outcomes than a protective effect in COVID-19." (PMID 37895256, 2023). "Although these data are limited, in aggregate they suggest that the various forms of AM all share the characteristic of activating both virus-associated (TLR3, TLR7, TLR8 or TLR9) and bacteria-associated (TLR2 and TLR4) innate receptors with severe COVID-19, KD and MIS-C." (PMID 36769320, 2023). "In recent studies, TLR2 was reported to be a potential therapeutic target for COVID-19." (PMID 35205112, 2022). "In this work, we observed an overexpression of TLR2 and its coupled MyD88 adaptor in tracheal tissue from COVID-19/B.1.1.7 patients (p < 0.0001 vs. COVID-19/B.1 patients), while only MyD88 was overexpressed in COVID-19/B.1 variant (p = 0.0077 vs. control patients)." (PMID 36498845, 2022). "However, other authors showed that recombinant SARS-CoV-2 S protein increased NLRP3 protein expression and induction of IL-1β in macrophages from patients with COVID-19 through the up-stream activation of TLR2." (PMID 36498845, 2022). "We demonstrated that antagonistic mAbs against anti-CLEC5A mAb and anti-TLR2 mAb can inhibit COVID-19-EVs-induced NET formation, and generated clec5a−/−/tlr2−/− mice to confirm the critical roles of CLEC5A and TLR2 in SARS-CoV-2-induced lung inflammation in vivo." (PMID 35820906, 2022). "Figuring out the relationship between peptide sequence in the lipopeptide and its TLR2 activity may lay the foundation for the rational design of novel lipopeptide adjuvant for COVID-19 vaccine." (PMID 35356002, 2022).
COVID-19 (continued). "Additionally, the comparison of COVID-19-related pneumonia cases and the control group revealed a significant result for rs3804100-G (TLR2)." (PMID 36611413, 2022). "Several TLRs may be implicated in COVID-19 and in the effects of COVID-19 vaccines; however, the strongest evidence provisionally points to TLR4 and TLR2." (PMID 36142792, 2022). "In terms of innate immunity, we showed that TLR2 and its adaptor MyD88 were overexpressed in tracheal biopsies of COVID-19 patients, which could contribute to the exaggerated inflammasome activation in COVID-19." (PMID 36498845, 2022). "It was found that the expression of TLR2 and MyD88 was related to the severity of COVID-19." (PMID 35935817, 2022). "From the currently available data, it is assumed that TLRs, mainly TLR2 and TLR4, may play a pathogenic role by inducing hyperinflammation, and thus, may lead to severe COVID-19." (PMID 34835108, 2021). "The top five targets identified based on candidate gene prioritization were C3, CFB, EGFR, IL6, and TLR2, where the 39 common core genes were used as a test set, and 1899 genes from the COVID-19 pathway (KEGG) and our multi-omics datasets were used as training sets." (PMID 34067609, 2021). "Taken together, these data reveal a mechanism for the cytokine storm during SARS-CoV-2 infection and suggest that TLR2 could be a potential therapeutic target for COVID-19." (PMID 34866574, 2021). "Increased expression of HIF-1α mRNA has also been reported in myeloid blood cells from critically ill COVID-19 patients, along with the expression of other genes, TLR2 and TLR4, which could be involved in SARS-CoV-2 sensing." (PMID 34835108, 2021). "Last, computational perturbation of genes involved in causal feedback loops identified versican (VCAN), an extracellular matrix glycoprotein, and Toll-like receptor 2 (TLR2) as novel target proteins for alleviating the hyperinflammatory response in patients with COVID-19 with severe symptomatology." (PMID 33536217, 2021). "Here we assessed the expression of TLR-2, TLR-4, and peptidoglycan recognition protein (PGRP)-4 and evaluated the association of changes in these markers as it related to SARS-COV-2 infection in the saliva of hospitalized patients with COVID-19." (PMID 34707585, 2021). "Our finding that SARS-CoV-2 S protein is a potent viral PAMP involved in the induction of inflammatory cytokines and chemokines via TLR2-dependent activation of the NF-κB pathway, therefore, is a valuable addition to the tremendous scientific effort aiming at combating COVID-19." (PMID 34866574, 2021). "GRP78 has been identified as a danger-associated molecular pattern (DAMP) for the toll-like receptors TLR2 and TLR3 and may cause increased inflammation in COVID-19 patients." (PMID 34770863, 2021). "This study suggests that TLR2 or its downstream signaling adapters could be therapeutically targeted to mitigate hyperinflammatory response in COVID-19 patients." (PMID 34866574, 2021). "In summary, TLR2/4 activation mediated by the S protein may play a crucial role in acute lung injury, cardiac complications, and other severe inflammatory responses observed in patients with both severe COVID-19 and LC." (PMID 40431631, 2025). "Our findings, which align with a previous report on the Brazilian population, suggest that the TLR2 rs3804100 variant may not be a significant factor in developing symptomatic COVID-19." (PMID 39456843, 2024). "Notably, CD44, previously reported to regulate the TLR2-mediated macrophage activation and proinflammatory responses, was also found to be significantly increased in ROIs in islet, ductal, and exocrine areas of COVID-19 samples." (PMID 39232561, 2024). "Our data support the notion that the host’s genetic background can significantly affect COVID-19 clinical phenotype, also suggesting that the IL18-rs1834481, TLR2-rs5743708, and TLR4-rs4986791 polymorphisms may be used as molecular predictors of COVID-19 clinical phenotype." (PMID 37766191, 2023).
COVID-19 (continued). "TLR2 mediated depression-like behaviors and dysosmia induced by envelope protein, which could serve as a promising therapeutic target for neurological manifestation in COVID-19 patients." (PMID 37158916, 2023). "Additionally, in COVID-19 patients, the level of TLR2 was positively related to disease severity." (PMID 37234160, 2023). "Yet, the knowledge about immunological effects of OxPAPC remains controversial, as other studies have indicated that it may function as a TLR4 and TLR2 agonist both in vitro and in vivo, overall limiting its potential as drug to inhibit hyperinflammation in severe COVID-19 [19,]." (PMID 38034686, 2023). "Therefore, TLR2 plays an important role in B cell maturation and may be treated as a potential therapeutic target in the treatment of COVID-19." (PMID 35528178, 2022). "Thus, severe and lethal immunopathological manifestations in reported in COVID-19 may be in part attributed by amplification of TLR2 and 4 inflammatory pathways through synergism with Dectin-1." (PMID 33498183, 2021). "However, due to increased expression of TLR4 and activating DAMPs of TLR2 and 4 in patients with COVID-19, Dectin-1 may participate in cross-communication with TLRs during S protein and DAMP identification and stimulation." (PMID 33498183, 2021). "In serum samples, soluble TLR-2 and TLR-4, IL-1β, IL-4, IL-6, Il-10, IFN-α, and TNF-α levels were significantly decreased in patients with coronavirus disease-19 (COVID-19) as compared with other viruses (p < 0.05 in each)." (PMID 41766850, 2026). "The GS ‘Coronavirus disease—COVID-19’ included several downregulated genes involved in innate immunity and inflammation, such as C-X-C motif chemokine ligand 8 (CXCL8) and toll like receptor 2 (TLR2)." (PMID 40559872, 2025). "Toll-Like Receptor 2 (TLR2) expression increased with moderate and severe COVID-19, suggesting its role in recognizing pathogens and triggering immune responses." (PMID 39928675, 2025). "After the validation set (GSE171110) analysis, only four genes, namely IL-6R, TLR4, TLR2, and IFNG, showed expression changes similar to those of the training set in COVID-19." (PMID 38165854, 2024). "A second study investigated the possible contribution of SNPs in TLR2 and TLR4 genes to COVID-19 disease severity and prognosis in an European population (N = 249) consisting mainly of Greek patients with SARS-CoV-2 infection." (PMID 38433829, 2024). "GSE164805 and GSE171110 dataset validation revealed significant differences between the COVID-19 and normal controls in four core genes (feature genes), namely IL6R, TLR4, TLR2, and IFNG." (PMID 38165854, 2024). "The CSF2, IFNG, and IL1B expression levels were considerably lower in the COVID-19 than in the Healthy group, while those of IL6R, TLR2, TLR4, and TNF were higher." (PMID 38165854, 2024). "The TLR-1/TLR-2 heterodimer binding SARS-CoV-2 S protein contributes to the inflammatory state and lung injury seen in COVID-19." (PMID 39456843, 2024). "Studies have shown that the expression of TLR2 and its downstream MYD88 is correlated with COVID-19 severity and can sense the SARS-CoV-2 envelope protein to produce inflammatory cytokines." (PMID 38165854, 2024). "Studies of innate activation unrelated to COVID-19 are also very limited, revealing TLR1, TLR2, TLR3, TLR4, TLR7 and TLR8 activation." (PMID 36769320, 2023). "Severe COVID-19, however, is characterized by additional activation of TLR1, TLR2, TLR4, TLR5, TLR6, NOD1 and NOD2, which are primarily responsive to bacterial antigens." (PMID 36769320, 2023). "We assessed the immunogenicity and protective efficacy of an experimental COVID-19 vaccine based on the SARS-CoV-2 Spike trimer formulated with a novel adjuvant LP-GMP, comprising TLR2 and STING agonists." (PMID 37179389, 2023). "In COVID-19 hearts, we identified significant upregulation of pro-inflammatory genes IL1B, IL-6, IL8, and the toll-like receptor TLR2." (PMID 36371548, 2023).